NLRP3 (NLR family pyrin domain containing 3)
Diseases named in the same sentence as NLRP3 in open-access papers (continued):
Sharing a sentence is not in itself a finding about the gene and the disease.
Hypertension (continued). "Among several types of inflammasomes NLR family CARD domain-containing protein 4 (NLRC4), NLRP6 and NLRP9, NLRP3 is most studied inflammasome in hypertension." (PMID 36620210, 2022). "In aggregate, NLRP3 and its inflammasome greatly contribute to the development and further damages of hypertension." (PMID 36204568, 2022). "Inhibition of NLRP3 inflammasome activity with MCC950 ameliorates hypertension, renal inflammation and fibrosis in DOCA-salt treated mice." (PMID 36620210, 2022). "Nucleotide-binding oligomerization domain-like receptor protein 3 (NLRP3) inflammatory vesicles activate caspase-1 and thus induce inflammation, thus becoming another new focus for triggering hypertension." (PMID 35295586, 2022). "We further found that intragastric administration of curcumin attenuated hypertension, repressed NF-κB activation, NLRP3 and MMP-9 expressions in the aortas, reduced the media thickness and the ratio of media thickness to lumen diameter in the aortas of SHR." (PMID 35530510, 2022). "It has been observed that the rise of cytokines such as IL-6 and CCL2 in the high-salt diet-induced hypertension rat model is connected with the NLRP3 inflammatory mechanism." (PMID 36035920, 2022). "Collectively, our findings indicated that miR-135a-5p over-expression inhibited TXNIP expression to block the binding of TXNIP and NLRP3, thereby alleviating hypertensive cardiac inflammation and fibrosis." (PMID 35148667, 2022). "While augmentation of NLRP3 expression by Ang II in renal cells and in kidneys of chronic Ang II-induced hypertension models has been demonstrated, mitigation of the NLRP3 expression by immunosuppression in hypertension is a novel observation." (PMID 35887028, 2022). "Emerging evidence suggests that oxidative stress and activation of the NLRP3 inflammasome drive high sodium-mediated activation of APCs and T cells and contribute to the development of renal and vascular inflammation and hypertension." (PMID 36620210, 2022). "Other reports in the literature underline the possible role of noncoding RNAs, which are emerging biomarkers in the hypertension field, as regulators of endothelial function via the NLRP3 inflammasome signaling pathway." (PMID 33494430, 2021). "The effects of modulation of the NLRP3 inflammasome pathway in the hypothalamus in a wider variety of animal models of hypertension are needed to achieve a deeper understanding of its role in the control of systemic blood pressure." (PMID 33494430, 2021). "Downregulation of the expression of key components of the NLRP3 inflammasome delays the development of hypertension and pharmacological inhibition of this inflammasome leads to reduced blood pressure in animal models and humans." (PMID 33494430, 2021). "Supporting the critical role of the NLRP3 inflammasome in the development of hypertension, genetic interventions to knockout NLRP3 or ASC proved to prevent the elevation of blood pressure observed in the mouse two kidney, one clip (2K1C) model of hypertension." (PMID 33494430, 2021). "In this model, allopurinol (ALLO), an NLRP3 inhibitor, significantly improved hypertension, proteinuria and interstitial inflammation and fibrosis." (PMID 34305953, 2021). "ASC−/− mice exhibited a sluggish pressor response and the treatment of NLRP3 inflammasome inhibitor MCC950 reversed the hypertension in 1K/DOCA/salt treated mice." (PMID 34305953, 2021). "So far, some literatures have confirmed the important role of NLRP3 activation in hypertension-related nephropathy, but the specific regulatory mechanism still needs to be further explored." (PMID 34305953, 2021). "In mice with deoxycorticosterone acetate and saline (1K/DOCA/salt)-induced hypertension, the mRNA levels of NLRP3, ASC, pro-caspase-1 and pro-IL-1β were evaluated, as well as the protein expression of active caspase-1 and mature IL-1β." (PMID 34305953, 2021).
Hypertension (continued). "In a stress-induced hypertension rat model, prorenin increased the ROS-triggering M1 phenotype-switching and NLRP3 activation, while NLRP3 inhibitor MCC950 decreased the M1 polarization in the rostral ventrolateral medulla." (PMID 34899720, 2021). "Increasing studies have confirmed that NLRP3 inflammasome is involved in the occurrence and development of hypertension." (PMID 34331512, 2021). "The components of the NLRP3 inflammasome are expressed in macrophages and foam cells within human carotid atherosclerotic plaques and VSMCs in hypertension." (PMID 35008765, 2021). "IL-1β and IL-18 are products of activated NLRP3 inflammasome; therefore, its role in the development of hypertension was investigated." (PMID 32650532, 2020). "It suggested that the effect of H2S on NLRP3 has potential therapeutic function in the treatment of hypertension." (PMID 33110394, 2020). "It has been demonstrated that the NLRP3 inflammasome contributes to vascular smooth muscle cell phenotype switching, proliferation, and vascular remodeling in hypertension." (PMID 32733235, 2020). "A promising treatment for hypertension involves inhibiting the activity of the NLRP3 inflammasome and stopping the vicious cycle of inflammation and endothelial injury." (PMID 33633569, 2020). "The expression of NLRP3 mRNA in renal biopsy specimens of patients with hypertensive or vascular nephrosclerosis is higher than that in normal kidneys, suggesting that NLRP3 plays a role in hypertension-related kidney disease." (PMID 32410864, 2020). "This study proved that ST has evident anti-inflammatory and protective effects on the endothelial function in hypertension, and that the NLRP3 inflammasome is also a pharmacological target of ST that can be used for effective hypertension treatment." (PMID 33633569, 2020). "It has been reported that high-salt-induced hypertension activates the sympathetic nervous system through nuclear factor-κB (NF-κB) and increased NLRP3 and IL-1β." (PMID 33633569, 2020). "In a transverse aortic constriction (TAC) mouse model, a widely use animal model of hypertension, NLRP3 inflammasome component expression was significantly increased while cardiac function was impaired." (PMID 32545788, 2020). "Our experiments have shown that ST improves vascular endothelial function by inhibiting the activation of the NLRP3 inflammasome, thus protecting against the endothelial injury of hypertension." (PMID 33633569, 2020). "Taken together, our data suggest that renal ELA exerts its beneficial roles in DOCA/salt-induced hypertension via blocking NADPH oxidase/ROS/NLRP3 inflammasome pathway, which is independent on its endogenous receptor APJ." (PMID 32829380, 2020). "The regulation of blood pressure includes neuroregulation (mainly the sympathetic nervous system) and humoral regulation (mainly the RAAS), while the NLRP3 inflammasome plays an important role in the neurohumoral regulation of hypertension." (PMID 33633569, 2020). "Attenuation of NLRP3 and caspase by chronic inhibition of NF-kB attenuates high salt induced hypertension." (PMID 32596261, 2020). "The link between prorenin and NLRP3 in microglia provides insights for the treatment of stress-related hypertension." (PMID 32242284, 2020). "In a murine model of hypertension, a highly selective SGK1 inhibitor, EMD638683, was shown to suppress IL-1β release, NLRP3 expression, and caspase-1 activation which was associated by reduced transformation of fibroblasts to myofibroblasts." (PMID 32596261, 2020). "In vivo, we used confocal microscopy to study the expression of tight junction proteins zonula occludens‐1/2 (ZO‐1/2) and the formation of NLRP3 inflammasome in coronary arteries of hypertension." (PMID 32573820, 2020). "In rats, salt-induced hypertension occurs partly due to the role of NLRP3 inflammasome activation in the hypothalamic paraventricular nucleus, while blockade of brain NLRP3 attenuates the hypertensive response." (PMID 32161574, 2020).
Hypertension (continued). "The NLRP3 inflammasome is activated in obese patients with hypertension to a higher extent compared to hypertensive dialysis patients." (PMID 33114648, 2020). "Our data demonstrate that ELA prevents DOCA/salt-induced hypertension by inhibiting NADPH oxidase/ROS/NLRP3 pathway in the kidney, which is APJ independent." (PMID 32829380, 2020). "The results showed that ST alleviated the inflammation in hypertension, which manifested as reduced NLRP3 and caspase-1 levels, and demonstrated that ST had an inhibitory effect on the activation of the NLRP3 inflammasome." (PMID 33633569, 2020). "It was shown that the activation of the NLRP3 inflammasome accelerated endothelial injury in hypertension and promoted an increase in blood pressure." (PMID 33633569, 2020). "Previous research found that activation of the NLRP3 inflammasome results in endothelial injury in hypertension, while ST inhibits the expression of NLRP3 and caspase-1, restraining the activity of the NLRP3 inflammasome." (PMID 33633569, 2020). "In summary, our results show that alleviative NLRP3 inflammasome activation attenuates hypertensive endothelial damage and ST ameliorates vascular endothelial dysfunction in hypertension via inhibiting activation of the NLRP3 inflammasome." (PMID 33633569, 2020). "Immunohistochemical analysis further revealed that TGF-beta and NLRP3 inflammasome activation [high-mobility group box 1 (HMGB1), IL-1beta, and NLRP3] were significantly upregulated in the kidney of rats with Ang II-induced hypertension." (PMID 32117956, 2020). "The present study aims to investigate the contribution of TGF-beta-mediated NLRP3 inflammasome to renal fibrosis in rats with high blood pressure." (PMID 32117956, 2020). "In this study, we tested the role and mechanism of calcium-sensing receptor (CaSR) in NLRP3 inflammasome activation during hypertension." (PMID 30906225, 2019). "Previous studies have reported that proinflammatory cytokines, IL-1β and IL-18, downstream targets of NLRP3 inflammasome, participate in the pathophysiology of cardiovascular disease and hypertension." (PMID 30906225, 2019). "Different groups have also provided evidence that aldosterone excess contributes to increased hypertension and fibrosis, and induces renal tubular cell injury via MR and mitochondrial ROS-mediated NLRP3 activation." (PMID 31817997, 2019). "Recently, NLRP3 inflammasome activation has been shown to be involved in various pregnancy complications, such as preeclampsia, spontaneous preterm labor, and hypertension in pregnancy." (PMID 31035323, 2019). "And NLRP3 inflammasome was involved with CaSR-mediated fibrosis during hypertension, which led to IL-1β and IL-18 release." (PMID 30906225, 2019). "Nevertheless, NLRP3 is suggested to be a critical component among the multiple factors that induce hypertension." (PMID 31694192, 2019). "It is noteworthy that compared with young adult rats, greater renal expression of NLRP3 and caspase-1 is reported to occur in old rats and so it is plausible that inflammation-driven hypertension is augmented in old age." (PMID 28659507, 2017). "Silencing of NLRP3 gene ameliorated hypertension, vascular remodeling, NLRP3 inflammasome activation and phenotype switching in the aorta of SHR." (PMID 28981106, 2017). "The present study was designed to determine the roles and mechanisms of NLRP3 inflammasome in phenotypic modulation and proliferation of vascular smooth muscle cells (VSMCs) in hypertension." (PMID 28981106, 2017). "Despite having higher renal expression of Nlrp3, Casp-1 and Il-1β, Ang II-induced hypertension (SBP: 139±7 mmHg) was unaffected by co-infusion of the NLRP3 inflammasome inhibitor, MCC950 (10 mg/kg/d; SBP: 145±10 mmHg)." (PMID 28659507, 2017). "Increased histone acetylation and subsequent NFκB activation in hypertension contribute to the NLRP3 inflammasome formation and activation." (PMID 28981106, 2017).
Hypertension (continued). "Thirdly, we tested the effect of MCC950, an NLRP3 inhibitor, on Ang II-induced hypertension in aged mice." (PMID 28659507, 2017). "We found that Ang II induced significant and similar increase of SBP in mitoTEMPO-treated and NLRP3 KO mice compared to the WT controls, demonstrating the hypertension-independent protection of mitoTEMPO and NLRP3 deletion." (PMID 27509058, 2016). "NF-κB/NLRP3 signaling pathway is a primary mechanism underlying vascular aging induced by bioaerosols in PM2.5, which further highlight the role of NF-κB in vascular aging and hypertension." (PMID 41507140, 2026). "NLRP3 inflammasome activation contributes to angiotensin II-induced vascular smooth muscle cell phenotypic transformation, proliferation, vascular remodeling, and hypertension." (PMID 40433411, 2025). "The NLRP3 inflammasome plays a crucial role in hypertension." (PMID 40572711, 2025). "Interestingly, chrysanthemum indicum extract, a traditional herbal medicine using for hypertension, inhibits NLRP3 and AIM2 inflammasome activation via regulating ASC phosphorylation in mice." (PMID 40433411, 2025). "NLRP3 concentrations in saliva (p = 0.040) and serum (p = 0.002) were significantly different among the four groups, with the highest levels observed in the periodontitis and hypertension group." (PMID 40572711, 2025). "This further supports the pivotal role of NLRP3 inflammasome in the development of hypertension." (PMID 40433411, 2025). "In rats, CaSR mediates NLRP3 activation in the context of hypertension and AMI." (PMID 40079000, 2025). "In murine models of preeclampsia, pharmacological inhibition or genetic deletion of NLRP3 mitigates hypertension, improves fetal outcomes, and restores spiral artery remodeling—highlighting a causative role for inflammasome-mediated inflammation in vascular maladaptation." (PMID 41008958, 2025). "Treatment for hypertension appears to target NLRP3 in a novel way." (PMID 40079000, 2025). "The activation of the NLRP3 inflammasome plays an instrumental role in promoting the phenotypic transformation of VSMCs induced by AngII, as well as driving cellular proliferation, vascular remodeling, and the progression of hypertension." (PMID 39974735, 2025). "Notably, NLRP3 inhibitors like MCC950 have demonstrated a reduction in blood pressure in animals with established hypertension." (PMID 38317229, 2024). "Overall, we hypothesize that oxidative stress and NLRP3 inflammasome-dependent pyroptosis are critical in the pathogenesis of hypertension-induced ED." (PMID 39877365, 2024). "We hypothesized that asprosin might led to vascular inflammation in hypertension via NLRP3 inflammasome formation." (PMID 38841464, 2024). "In a recent study, VEGFC was shown to inhibit the activation of NLRP3 inflammatory vesicles by promoting autophagy to ameliorate sensitized hypertension and nephritis, which may be a potential therapeutic target for HTN." (PMID 38545112, 2024). "Increased NLRP3 inflammasome activity is necessary for high salt diet-induced increase in IL-1β expression and for increased blood pressure in an angiotensin II-primed mouse model of hypertension." (PMID 37293263, 2023). "However, the functional significance of the inflammasome in renal afferent arteriole regulation remains poorly understood, and the mechanisms mediating the activation and regulation of NLRP3 inflammasome in Ang II-dependent hypertension need to be defined." (PMID 37511174, 2023). "Both myeloid-derived NLRP3 inflammasome and IsoLGs contribute to the pathogenesis of hypertension." (PMID 37293263, 2023). "Also, NLRP3 is essential for hypertension development in the DOCA/salt model, mainly due to increased leukocyte recruitment and consequent renal fibrosis." (PMID 36515571, 2023). "NLRP3 activation results in caspase-1 activation and subsequent secretion of IL-1β and IL-18, the plasma levels of which are consistently high in patients with hypertension." (PMID 36620210, 2022).
Hypertension (continued). "TMAO could cross the blood-brain barrier (BBB) and promote oligodendrocytes pyroptosis via ROS/NLRP3 inflammasome signaling and mitochondrial dysfunction to promote demyelination, revealing a new diagnostic marker for WML under hypertension." (PMID 36072486, 2022). "Besides, the research shows that the downregulation of the expression of key components of the NLRP3 inflammasome can delay the development of hypertension." (PMID 36187801, 2022). "Meanwhile, several studies revealed that smoking, hypertension and diet with rich in saturated fatty acids and glucose might coordinatingly contribute to NLRP3 activation in myeloid cells of the AS patients." (PMID 35493086, 2022). "Thus, no changes in intrarenal AIM2 levels in Ang II-infused rats are expected and the results highlight specific regulation of renal NLRP3 in hypertension." (PMID 35887028, 2022). "Furthermore, the expression of NLRP3, which is a component of inflammasome, is augmented by Ang II in renal cells and in kidneys of chronic Ang II-induced hypertension models." (PMID 35887028, 2022). "Increased NLRP3 inflammasome activity has been reported in a murine model of hypertension." (PMID 34485175, 2021). "Elevated activation levels of the key NLRP3 inflammasome priming factor, NF-κB, in tissue and inflammatory cells are persistent in hypertension and result in exaggerated levels of circulating and tissue IL-1β and IL-18 in patients with essential hypertension and in animal models of the disease." (PMID 33494430, 2021). "In hypertension, various mediators lead to the NLRP3 inflammasome formation and activation." (PMID 34575833, 2021). "There is literature supporting the role of the NLRP3 in hypertension." (PMID 32596261, 2020). "Conversely, an increased histone acetylation at the NLRP3 promoter and NF-kB activation contributes to the activation of the NLRP3 inflammasome in vascular smooth muscle cells and consequent phenotypic changes and proliferation in hypertension." (PMID 32796686, 2020). "Interestingly, Losartan, an angiotensin II receptor blocker used to treat hypertension, inhibits LPS/ATP-induced IL-1β secretion by suppressing NLRP3 inflammasome." (PMID 33664731, 2020). "Activation of NLRP3 inflammasome through redox-dependent processes has been shown in Ang II–mediated and DOCA/salt hypertension and in preeclampsia, pulmonary hypertension, and hypertension-associated kidney dysfunction." (PMID 32389339, 2020). "Aloe Emodin improves endothelial junction dysfunction by inhibiting NLRP3 inflammasome activation through NLRP3 ubiquitination; may have specific therapeutic value in hypertension‐related cardiovascular disease." (PMID 32573820, 2020). "We demonstrated that MCMV infection may be another mechanism of Ednra activation, promoting hypertension-related myocardial remodeling through cascade activation of the NLRP3 inflammasome." (PMID 33457411, 2020). "Deficiency of NLRP3 inflammasome components attenuates the development of AngII-induced hypertension, but does not affect FGR, proteinuria, or sFlt1 levels." (PMID 32161574, 2020). "Inhibiting NF-κB activity reduced NLRP3 and IL-1β levels, thereby reducing hypertension." (PMID 33633569, 2020). "Our data demonstrate that ELA may prevent DOCA/salt-induced hypertension by blocking NADPH oxidase/ROS/NLRP3 signaling pathway in the kidney, which is APJ independent." (PMID 32829380, 2020). "In this model, it is speculated that CaSR activation in VSMCs increases cytosolic [Ca2+]i, which stimulates NLRP3 inflammasome activation and leads to IL-1β and IL-18 maturation during hypertensive aortic fibrosis." (PMID 30906225, 2019). "The NLRP3 inflammasome, a key signaling platform that activates highly proinflammatory cytokines, IL-1β and IL-18, contributes to the development of aortic aneurysms and hypertension via vascular inflammation." (PMID 30906225, 2019).